IL6 (interleukin 6)
Diseases named in the same sentence as IL6 in open-access papers (continued):
Sharing a sentence is not in itself a finding about the gene and the disease.
Obesity (continued). "Obesity, hypertension and type 2 diabetes are the most common comorbidities, that lead to increased levels of inflammatory biomarkers such as interleukin-6 (IL-6) and tumor necrosis factor-α (TNF-α)." (PMID 33945586, 2021). "Obesity impacts adipocytes to secrete proinflammatory cytokines such as interleukin (IL)-6 and tumor necrosis factor-α (TNF-α), and lipotoxicity induces hepatocyte death to activate Kupffer cells to produce those cytokines." (PMID 35002979, 2021). "Loss of adipocyte functionality, as it occurs in obesity, is accompanied by the secretion of proinflammatory cytokines, as tumor necrosis factor alpha (TNF-α) and interleukin 6 (IL-6)." (PMID 34206506, 2021). "Studies have reported that pro-inflammatory cytokines like interleukin 6 and interleukin 18 are elevated in obesity and that this occurs in parallel with changes to other inflammatory mediators as well as the development of insulin resistance." (PMID 34086911, 2021). "Obesity is linked to an increased risk of tumour development and was shown to promote HCC formation via enhanced TNF α and IL-6 secretion." (PMID 34047814, 2021). "In RRMS patients with obesity, increased CSF levels of pro-inflammatory interleukin 6 (IL-6) and decreased levels of anti-inflammatory IL13 are reported." (PMID 34639186, 2021). "IL-6: Just as in the case of TNF-α, obesity and insulin resistance cause an increase in interleukin 6 (IL-6), through its overproduction by adipocytes and fibroblasts." (PMID 34948466, 2021). "Specifically, deciphering the role of the LGI marker IL-6 in obesity has been emphasized over the past decade." (PMID 34835991, 2021). "IL-6 is a critical signaling molecule released from fat cells and belongs to obesity-related cytokines." (PMID 33530554, 2021). "On the other hand, obesity, diabetes mellitus, and raised serum IL-6 levels were predictive of poor pregnancy outcomes in the course of COVID-19 infection." (PMID 33530554, 2021). "In human cohorts, CLS-B positively correlates with older age, obesity, dyslipidemia and higher levels of glucose, insulin, C-reactive protein and IL-6." (PMID 34294716, 2021). "As results, the identified findings using network pharmacology analysis had identified total six hug genes of metformin treating obesity/hypertension, including IL6, CCL2, LEP, APOB, SERPINE1, and APOE." (PMID 34334083, 2021). "Obesity is associated with overproduction of leptin, leading to leptin-induced local and peripheral inflammation via the activation of TNF-α and IL-6 production, and stimulation of surface markers." (PMID 34844584, 2021). "IL6 is abundantly expressed in adipose tissue, with elevated secretion by adipose tissue observed in individuals with obesity." (PMID 34063273, 2021). "It was well known that ATM were major sources for increased systemic IL-6 levels in obesity in mice." (PMID 34504646, 2021). "Obesity was associated with an increased ratio of M1/M2-like ATM in WAT, favoring generation of cytokines such as IL-6 and promoting adipocyte lipolysis, ectopic lipid accumulation, and insulin resistance." (PMID 34504646, 2021). "Since obesity is characterized by changes in metabolic profile and chronic low-grade inflammation, we first measured plasma levels of IL-6, CRP, and metabolic hormones." (PMID 34195568, 2021). "Obesity is currently presented as a pro-inflammatory state with an expansion in the outflow of inflammatory cytokines, such as interleukin-6 (IL-6) and tumor necrosis factor-alpha (TNF-α), alongside the expanded emission of leptin." (PMID 33946540, 2021). "As adiponectin is mainly produced and secreted by white adipocytes, these data suggest that IL-6 signaling in adipocytes contributes to reduced circulating adiponectin leptin levels in people with obesity." (PMID 33572989, 2021).
Obesity (continued). "IL-6 is a proinflammatory cytokine involved in immunoregulation, cell growth and differentiation, as well as in obesity-related insulin-resistance and chronic inflammatory condition: plasma IL-6 levels positively correlated to weight gain in humans." (PMID 34830209, 2021). "It turned out that obesity would be confusing the relation between IL-6 and nickel, by increasing the influence of nickel in the inflammatory status of individuals in over 40% (from 25% to 36%) when including BMI in the model." (PMID 33546415, 2021). "Since elevated levels of IL-1β and TNFα have been previously linked to obesity-induced inflammation and the development of insulin resistance in adipose tissue adipokines, we investigated whether these two agents interact to trigger IL-6 production in adipocytes." (PMID 34831450, 2021). "In diabetes and obesity, increased levels of IL-6 and TNF-α have been demonstrated, whereas the serum levels of IL-6 and CRP have been shown to predict the future occurrence of diabetes mellitus type 2." (PMID 34452136, 2021). "STAT3 is the main signaling factor of IL-6, and obesity has been shown to chronically activate intracellular JAK-STAT3 signaling through increased levels of IL-6 and leptin." (PMID 35087513, 2021). "IL-6 production was also elevated by viral infections and obesity, two important comorbid factors resulting in asthma exacerbations and severity." (PMID 33925531, 2021). "Circulating IL-6 lvels were analyzed in 17 studies, in which 439 participants with overweight and obesity were involved in a training program." (PMID 34948868, 2021). "In contrast to leptin, TGF-β1 can increase IL-6 mRNA expression and IL-6 protein release, as recently reported in the field of obesity and metabolic syndrome." (PMID 34327205, 2021). "In fact, obesity was demonstrated to be a positive regulator of IL-6 and IL-6 receptor levels in subcutaneous WAT, which contributed to induction of inflammation and obesity-associated metabolic dysfunctions in mice." (PMID 34504646, 2021). "Obesity is associated with increased inflammation in adipose tissue, with monocyte chemoattractant protein 1 (MCP-1), IL-6, toll-like receptor 4 (TLR4), and TNFα elevated in adipose tissue of obese relative to lean individuals." (PMID 34149621, 2021). "According with reported literature, V-ASCs, isolated from CRC patients with obesity, produce more abundant IL-6 and HGF as compared with S-ASCs, CR-CSphCs, and primary adipose tissue cells (AT)." (PMID 34408135, 2021). "Like leptin, IL‐6 and TNF‐α are produced and released from human adipocytes, and their elevated levels have been found to be strongly associated with all measures of obesity in other studies from Europe or the United States." (PMID 33680494, 2021). "Although it is known that hepcidin rises when IL-6 increases, the relationship between hepcidin, dyslipidemia, IR and visceral adiposity in adolescents with obesity is unclear." (PMID 34065056, 2021). "Given the relevant role of IL-6 in obesity and some asthma endotypes, numerous studies have examined the potential bridging role of IL-6 for these two conditions and have reported contradictory findings." (PMID 33418879, 2021). "Obesity is often associated with an increased risk of systemic inflammation through production of TNF-α and IL-6 from adipocytes." (PMID 34239993, 2021). "Serum IL-6 levels have been found to be higher in obese subjects and correlated with all indexes of obesity and with visceral adipocytes." (PMID 33418879, 2021). "Visceral fat tissue takes a greater part in obesity and produces highly proinflammatory cytokines, including IL-6, TNF-α, and IL-8, compared to its subcutaneous counterpart." (PMID 34737743, 2021). "In summary, the available evidence suggests increased circulating IL-6 and TNF-alpha, which are features of obesity associated insulin resistance, likely causally increase risk of CVD." (PMID 34760952, 2021).
Obesity (continued). "Our previous work has shown that women with obesity had significantly higher baseline IL-6, IL-10, TGF-β, and IL-12 compared with NWW." (PMID 33764994, 2021). "Increased levels of IL-6 have been reported in obesity and obesity-related multifactorial diseases, such as diabetes, insulin resistance, cardiovascular disease, osteoarthritis and cancers." (PMID 34680892, 2021). "For instance, in elderly mice given systemic anti-tumor immunotherapy, obesity caused a fatal cytokine storm, which increased M1 macrophage polarization, and proinflammatory TNF-α and IL-6 release, leading to a reduced anti-tumor effect and low survival rate." (PMID 34350120, 2021). "In patients with insulin resistance and obesity, the production and expression of IL-6, TNF-α, and MCP-1 are significantly increased." (PMID 33883996, 2021). "When we assessed the CRT method only in the patients with obesity, we also found that the best predictor of mortality was IL-6." (PMID 33809913, 2021). "On the other hand, in adipose tissue, IL-6 signaling pathway activation promotes macrophage infiltration, leading to a chronic state of low-grade inflammation, as well as to obesity-related insulin resistance." (PMID 34502235, 2021). "There is a string associated with elevated fat cells and diabetes that makes the release of interleukin-6 from fat cells that triggers the pro-inflammatory state indicating obesity." (PMID 35223819, 2021). "Chronic low-grade inflammation, present in obesity and promoted by it, causes a decrease in muscle anabolic function, mediated by changes in the production of factors, such as TNF, IL-6, leptin and GH." (PMID 33802940, 2021). "On the other hand, obesity was recently recognized as a low-grade chronic inflammatory status, and IL-6 and TNF-α are considered as biomarkers of this condition." (PMID 34560886, 2021). "Butyrate, when administered in db/db diabetic mice with obesity via the I.P. route (1 g/kg), reduced the mRNA expression of inflammatory cytokines (interleukin 1, interleukin 6, and tumor necrosis factor α) in adipose tissue." (PMID 33801984, 2021). "Using this algorithm, all hug targets of metformin against obesity-related hypertension were identified accordingly, including IL6, CCL2, Leptin (LEP), Apolipoprotein B (APOB), serine protease inhibitor clade E member 1 (SERPINE1), Apolipoprotein E (APOE)." (PMID 34334083, 2021). "Increased ROS has also been linked to many metabolic alterations, such as insulin resistance, decreases in adiponectin, and increased expression of pro-inflammatory cytokines including TNFα and IL-6, all potential markers of obesity and cancer development." (PMID 33926456, 2021). "For instance, knockout animal studies have implicated pro-inflammatory cytokines, such as IL-6 and TNF-α, in the development of obesity." (PMID 34063221, 2021). "Following stimulation by IL6, Arid5a further represses Pparγ expression, which ameliorates adipogenesis and obesity." (PMID 35126382, 2021). "In obese white adipose tissue, proinflammatory M1 macrophages form crown-like structures surrounding the dead adipocytes, contributing to the obesity-induced low-grade inflammation and production of inflammatory cytokines such as IL-6." (PMID 34452063, 2021). "Inflammatory markers such as IL6, MCP1 and TNF-ɑ are secreted by adipocytes and are directly associated with high BMI, obesity and insulin resistance." (PMID 33593418, 2021). "This imbalance production of IL-6 and IL-10 was also confirmed in mitogen-stimulated B cells in individuals with obesity." (PMID 34206312, 2021). "A meta-analysis showed beneficial effects of exercise on the inflammatory status (CRP and interleukin-6) in adults with obesity." (PMID 34485407, 2021). "An analysis of other comorbidities, in our study, showed that IL-6 was correlated only with the presence of obesity and ischemic stroke, and only in the group of patients with macrovascular coronary lesions." (PMID 34683106, 2021).
Obesity (continued). "It should be noted that, the increased level of inflammatory cytokines were different in high-fat diet-induced obesity and genetic-induced obesity as IFNγ and TNF-α elevated in genetically-induced obesity, while IL-6 elevated in diet-induced obesity." (PMID 33827616, 2021). "The obesity skewed immune responsiveness, which broadly favors proinflammatory cytokine (e.g., IL-6, TNF) and chemokine (e.g., CCL2) production, is directly linked with obesity-driven metabolic derangements." (PMID 34099626, 2021). "Obesity is also associated with increased levels of circulating pro-inflammatory markers such as CRP, IL6, TNFalpha and other cytokines." (PMID 34154662, 2021). "Systemic knockout of TNF-α, IL-6 or TNFR1 all prevent obesity-induced cancer formation in HCC and PDAC suggesting a functional role of the immune apparatus." (PMID 33987528, 2021). "In a model including age, sex, arterial blood pressure, dyslipidemia, diabetes, steatosis, and drug use, only sex, adiponectin plasma levels, and obesity resulted significant predictors of IL-6 DNA methylation, independently of the other covariates." (PMID 34869683, 2021). "High leptin levels in aging and obesity upregulate the proinflammatory cytokines IL-6 and TNF-α, reducing insulin-like growth factor 1 (IGF1) activity and decreasing their anabolic actions on skeletal muscle." (PMID 34676021, 2021). "Leptin induces the expression of TNF-α, IL-6, and IL-1β in adipose tissue cells, contributing to insulin resistance, and is considered one of the links between obesity, insulin resistance, and atherosclerosis." (PMID 33520042, 2021). "IL-6 has emerged as one of the potential cytokines that link obesity-derived chronic inflammation with insulin resistance." (PMID 34831450, 2021). "Obesity is also associated with increased circulating concentrations of inflammatory markers such as C-reactive protein (CRP), interleukin-6 (IL-6), and tumor necrosis factor (TNF)-α." (PMID 33498671, 2021). "Obesity is characterized by an increased production of pro-inflammatory cytokines, such as interleukin-6 (IL-6) and tumor-necrosis factor α (TNFα), leading to a low chronic inflammatory state." (PMID 34940598, 2021). "Up-regulation of the pro-inflammatory cytokines tumour necrosis factor α (TNFα) and Interleukin 6 (IL-6) have previously been shown to decrease ApoA-IV expression at both the gene and protein level in obesity models in mice." (PMID 33918228, 2021). "MCP-1 is a chemoattractant which facilitates recruitment of macrophages into adipose tissue, and IL-6 production by macrophages is increased in adipose tissue in obesity." (PMID 34149621, 2021). "In 2016, we reported that maternal diet-induced obesity leads to increased serum IL-6 concentrations and upregulated hypothalamic and egWAT IL-6 signaling in the offspring at P21." (PMID 34835991, 2021). "Using PDB database, IL-6 and CCL2 proteins in obesity and hypertension were screened out, and then 1ALU in IL-6 was selected for docking with metformin biologically." (PMID 34334083, 2021). "A negative correlation was also observed between the total protein intake in PCOS patients and between overweight and obesity and the concentration of IL-6, TNF-α." (PMID 34441766, 2021). "Although IL-6 protects against obesity and insulin resistance, it can also be pro-inflammatory owing to its trans signaling, in which IL-6 binds soluble IL-6R and then forms a heterotrimer with gp130 expressed on the cell surface." (PMID 34576181, 2021). "In outbred mice, obesity-resistance is accompanied by increased expression of IL6 in the hypothalamus." (PMID 34465367, 2021). "Although the mechanisms underlying the development of sarcopenia obesity remain to be elucidated, chronic inflammation such as that induced by TNF-α and IL-6 signaling is a possible contributor to the development of sarcopenic obesity." (PMID 33399954, 2021).
Obesity (continued). "It has been reported before that Wnt5a is expressed in higher level in visceral adipocytes and specially in obesity, and that this increased expression correlates with higher IL6 expression in human samples." (PMID 35111744, 2021). "In patients with obesity, inflammatory cytokines, such as interleukin (IL)-1, IL-6, and TNF-α, increase and are reported to induce higher IR conditions." (PMID 34959901, 2021). "The role of interleukin-6 (IL-6) in the obesity-induced dysregulation of glucose metabolism in adipose tissue is controversial." (PMID 33572989, 2021). "We focused on the role of adipose IL-6 in ATM remodeling in the context of obesity and lipolysis for the reasons as follows." (PMID 34504646, 2021). "In a second step, a quasi‐linear association of obesity indices with leptin, CRP, IL‐6, and TNF‐α was investigated." (PMID 33680494, 2021). "Alterations in glucocorticoids, adipokines, insulin resistance and increased inflammatory mediators, including interleukin-6 and tumour necrosis factor alpha, are involved in obesity." (PMID 33706839, 2021). "Circulating plasma levels of several immuno-modulatory peptides, including TNFα, IL-6, IL-8, IL-10, IL-18 and C-reactive protein, were found to be elevated in human obesity." (PMID 34571976, 2021). "Adipose tissue secretes adipokines, including adiponectin, tumor necrosis factor-α (TNF-α), interleukin-6 (IL-6), IL-18, and leptin, to regulate obesity." (PMID 33997011, 2021). "Gene expression data of sorted ATDCs demonstrated that obese ATDCs show a higher expression of IL-12, IL-18, and IL-6, indicating that obesity induces ATDC activation and maturation." (PMID 34445379, 2021). "Circulating concentrations of interleukin (IL)-6 were significantly increased due to obesity (p = 0.002) and CC (p < 0.001)." (PMID 34445187, 2021). "The macrophage deposition and its chronic activation cause the abnormal secretion of IL-6, TNF-α during SARS-CoV-2 infection in a patient with obesity." (PMID 34220807, 2021). "Overweight/obesity strongly correlate with the levels of specific inflammatory markers, including IL-6." (PMID 34059769, 2021). "The biomarker of systemic inflammation, metabolic dysfunction, and obesity is IL-6 and its sputum and serum levels were increased in non-T2 asthma." (PMID 35055325, 2021). "Obesity significantly increased the levels of serum LPS and IL-6, and PDX treatment reversed these levels of serum markers of inflammation." (PMID 35185543, 2021). "TNF-α, Il-1β, IL-6 and IL-8 are involved both in the pathogenesis of HS as well as in the development of glucose intolerance, obesity, hyperlipidemia, metabolic syndrome and atherosclerosis." (PMID 34830597, 2021). "Visfatin synthesis increases in obesity and stimulates the expression of inflammatory cytokines such as IL-6 and TNF-α, adhesion molecules, metalloproteinases (MMP-2 and MMP-9), VSMCs proliferation and migration, and collagen synthesis." (PMID 34202323, 2021). "Secondly, we did not measure other inflammatory markers associated with hepcidin-25 or degree of obesity, such as CRP, IL-6, or erythrocyte sedimentation rate." (PMID 34258058, 2021). "Obesity is a metabolic disease characterized by a state of chronic, low-grade inflammation and dominated by pro-inflammatory cytokines such as IL-6." (PMID 34394118, 2021). "Pediatric populations with obesity tend to follow a similar pattern since a recent study underlined that leptin, IL6, and TNF α serum levels significantly correlate to body mass index in children with obesity." (PMID 34207683, 2021). "Due to the common link of both C-reactive protein and fibrinogen to the interleukin-6 gene promoter, those confounding effects such as nutritional status or obesity also influence the C-reactive protein level." (PMID 33747971, 2021).